BRD9 (bromodomain containing 9)
Diseases named in the same sentence as BRD9 in open-access papers (continued):
Sharing a sentence is not in itself a finding about the gene and the disease.
cutaneous melanoma (7 papers, 2020 to 2025). A primary melanoma arising from atypical melanocytes in the skin. "Loss of BRD9 expression was shown to occur in uveal and cutaneous melanoma cells by a mechanism involving recurrent mutations in a splicesomal factor, SF3B1." (PMID 35323214, 2022). "In summary, we have identified three novel mutations in CDH23, ARHGEF40, and BRD9 genes, which could confer cutaneous melanoma susceptibility." (PMID 32276436, 2020). "There is also evidence that BRD9 is potentially a tumour suppressor in both uveal and cutaneous melanoma." (PMID 39199954, 2024). "There is also evidence that BRD9 is potentially a tumor suppressor in both uveal and cutaneous melanoma and possibly other cancers." (PMID 35323214, 2022). "Although BRD9 amplifications occur more frequently in other cancers, the TCGA dataset indicates that BRD9 is the most frequently amplified SWI/SNF gene in cutaneous melanoma, closely followed by BICRAL1, which encodes another ncBAF component." (PMID 35323214, 2022). "The role of BRD9 in cancer was confirmed when knockout of BRD9 conferred a growth advantage to UVM, cutaneous melanoma, and pancreatic cancer cells." (PMID 34899861, 2021).
colon carcinoma (6 papers, 2022 to 2025). "The imperfect association between loss of BRD9 and c-Myc expression implicated additional factors in downregulating the oncoprotein in colon cancer cells." (PMID 36297001, 2022). "We observed that siRNA-mediated loss of BRD9 expression in human colon cancer cells produced marked changes in phenotypic and molecular readouts, consistent with the overarching goal of targeting oncogenic functions arising from BRD9 overexpression." (PMID 36297001, 2022). "The biological functions of BRD9 and the signalling pathway involved were also explored in cell lines related to lung cancer and colon cancer." (PMID 38303608, 2024). "BRD9 knockdown also resulted in the inhibition of colony formation in lung cancer cells and colon cancer cells." (PMID 38303608, 2024). "Similar with lung cancer, the staining of BRD9 in colon cancer, including adenocarcinoma, mucinous adenocarcinoma and signet‐ring cell carcinoma, were also notably higher than the staining of BRD9 in normal colon tissues." (PMID 38303608, 2024). "Knocking down BRD9 led to the inhibition of lung and colon cancer development, likely via the Wnt/β‐catenin signalling pathway." (PMID 38303608, 2024). "Knockdown of BRD9 can inhibit the progression of lung and colon cancers through Wnt/β‐catenin signalling pathway." (PMID 38303608, 2024). "For experimental validation, high expression levels of BRD9 were observed in tumour tissue samples from both lung and colon cancer patients." (PMID 38303608, 2024). "Polyphenols mimicked BRD9 knockdown and iBRD9 treatment in reducing colon cancer cell viability, inhibiting colony formation, and enhancing DNA damage and apoptosis." (PMID 36297001, 2022). "Nonetheless, BRD9 expression and pRPA32 were interrelated, and up to a 6-fold increase in pH2AX and pRPA32 expression in colon cancer cells treated with iBRD9 or natural polyphenols suggests that DNA damage/repair pathways are worthy of further investigation." (PMID 36297001, 2022). "In tissue microarrays, BRD9 protein was immunolocalized mainly to the nucleus, and was strongly positive in colon cancers as compared to normal colon." (PMID 36297001, 2022). "Knockdown of BRD9 could inhibit the progression of lung and colon cancers through the Wnt/β‐catenin signalling pathway." (PMID 38303608, 2024). "According to our experimental results, BRD9 knockdown could inhibit the progression of lung and colon cancers by the Wnt/β‐catenin signalling pathway." (PMID 38303608, 2024). "In conclusion, we proposed that BRD9 represents a druggable vulnerability in colon cancer and I‐BRD9 could be effective to suppress COAD progression." (PMID 35778964, 2023). "Together, our study revealed previously unidentified roles of BRD9 in colon cancer metabolism and tumor progression, indicating that BRD9 could be a valuable therapeutic target for COAD patients." (PMID 35778964, 2023). "Our study revealed previously unidentified roles of BRD9 in colon cancer metabolism and tumor progression, indicating that BRD9 could be a valuable therapeutic target for COAD patients." (PMID 35778964, 2023). "I‐BRD9 inhibitor selectively targeting BRD9 could significantly suppress colon cancer cells in vitro and in vivo, representing a therapeutic vulnerability." (PMID 35778964, 2023). "We aimed to identify the biological roles and clinical significance of BRD9 in colon cancer." (PMID 35778964, 2023). "We report here that overexpression of BRD9 is associated with poor prognosis in CRC patients, and that siRNA-mediated knockdown of BRD9 decreased cell viability and activated apoptosis in human colon cancer cells, coincident with increased DNA damage." (PMID 36297001, 2022). "In metastasis lineage SW620 colon cancer cells, iBRD9 and predicted BRD9-inhibitory natural polyphenols exhibited concentration-dependent inhibition of cell viability and colony formation, with a significant increase in the percentage of cells undergoing apoptosis." (PMID 36297001, 2022).
colon carcinoma (continued). "In human colon cancer cells, knockdown of BRD9, pharmacologic inhibition with iBRD9, and targeting of BRD9 overexpression via natural polyphenols resulted in marked changes in phenotype and molecular readouts, whereas normal colonic epithelial cells were resistant." (PMID 36297001, 2022). "In contrast to normal tissues, the phosphorylation levels of the T103 locus, situated outside the bromodomain domain of BRD9, exhibited an increase in breast cancer and clear cell RCC tissues but a decrease in UCEC and colon cancer tissues." (PMID 38303608, 2024). "According to the results of flow cytometry, knockdown of BRD9 promoted apoptosis in lung cancer cells (ABC‐1 and LK‐2) and colon cancer cells (HT‐29 and SW480)." (PMID 38303608, 2024). "Particularly, we demonstrated that BRD9 mediates the enrichment of H3K27ac at ENO2 and ALDOC gene loci, thereby enhancing the glycolytic activities of colon cancer cells." (PMID 35778964, 2023). "Expectedly, knockout of BRD9 or I‐BRD9 treatment significantly inhibited glycolytic activities of cells, as indicated by decreased basal ECAR and maximal ECAR in colon cancer cells." (PMID 35778964, 2023). "Similarly, comparing the expression of BRD9 between normal colon cells (CRL1459) and five different colon cancer cell lines revealed that BRD9 was upregulated in colon cancer cells." (PMID 38303608, 2024). "Last but not least, the clinical and translational significance of BRD9 in colon cancer should be determined in more abundant in vivo assays, including patient‐derived tumor xenograft (PDX) and orthotopic colon cancer models." (PMID 35778964, 2023).
hepatocellular carcinoma (6 papers, 2020 to 2025). A malignant tumor that arises from hepatocytes. "In hepatocellular carcinoma, BRD9 promoted the proliferation, migration, invasion, and EMT of cancer cells." (PMID 36674511, 2023). "However, the expression and biological role of BRD9 in hepatocellular carcinoma (HCC) is poorly understood." (PMID 32908135, 2020). "Similar findings have been reported in hepatocellular carcinoma (HCC), with BRD9 overexpressed in HCC patients as well as promoting cell growth and metastasis, and its depletion and inhibition reducing these effects in HCC cells." (PMID 34944438, 2021).
lung carcinoma (6 papers, 2020 to 2025). "Although little is known about the function of BRD9, copy number gains of the BRD9 gene in lung cancer patients has been reported and was associated with lung cancer susceptibility." (PMID 32298288, 2020). "When comparing the staining of BRD9 in stage IIB lung cancers against normal lung tissues, only staining in LUSC was significantly higher." (PMID 38303608, 2024). "In conclusion, our results suggest novel molecular mechanisms whereby MEOX2 and GLI-1 may modulate functional dynamics between cBAF (SMARCB1) and ncBAF (BRD9) complexes, contributing to lung cancer progression." (PMID 39971779, 2025). "Furthermore, our results suggest that BRD9 may contribute to the activation of both lung cancer oncogenes GLI-1 and EGFR." (PMID 39971779, 2025). "Furthermore, these findings allow us to discuss that the inhibition of BRD9 may improve the therapeutical responses in lung cancer patients." (PMID 39971779, 2025). "Based on this, we conducted Co-IP assays using A549 lung cancer cells, which revealed that SMARCB1 interacts with MEOX2, GLI-1, and BRD9, with a potential weak interaction with CBP and EZH2." (PMID 39971779, 2025). "Comparison of BRD9 staining between normal lung tissues and stage IIIA lung cancers once again revealed significantly higher staining in both lung cancer subtypes." (PMID 38303608, 2024). "Comparing BRD9 expression in three different normal lung cell lines (BEAS‐2B, MRC‐9 and HLF) against each of the four different lung cancer cell lines (A549, ABC‐1, LK‐2 and EBC‐1) revealed significant upregulation of the gene in tumor." (PMID 38303608, 2024). "Furthermore, this study suggests that epigenetic regulators, including the NuRD (MTA2) and ncBAF (BRD9) complexes, contribute to EGFR and GLI-1 expression and interact with MEOX2 in lung cancer cells." (PMID 39971779, 2025).
uveal melanoma (6 papers, 2021 to 2024). A melanoma derived from melanocytes of the uveal tract. "In myelodysplasias (MDS) and uveal melanomas (UVM) with mutant SF3B1, BRD9 is reported to undergo alternative splicing leading to inclusion of a poison exon causing mRNA degradation, also implicating BRD9 as a potential oncogene in those tumors." (PMID 38816579, 2024). "Additionally, ASOs targeting aberrant BRD9 splicing in uveal melanoma have been shown to restore BRD9 protein levels preclinically." (PMID 39316554, 2024). "One of the mis-spliced genes identified in multiple SF3B1-mutated cancerous cell lines including erythroleukemic (K562) and uveal melanoma (UVM) is bromodomain containing 9 (BRD9), a component of the non-canonical BAF (ncBAF) chromatin remodeling complex." (PMID 34899861, 2021). "Recently, SF3B1 mutations in uveal melanoma (UVM), myelodysplastic syndrome (MDS), and CLL were associated with mis-splicing of Bromodomain Containing 9 (BRD9), a subunit of the non-canonical BRG1 (SMARCA4) or BRM (SMARCA2) associated factor (ncBAF) chromatin remodeling complex." (PMID 39261602, 2024).
breast carcinoma (5 papers, 2020 to 2026). "Both TET2 and BRD9 are located at previously GWAS-identified breast cancer risk loci (lead variants rs62331150 and rs2853669)." (PMID 38697998, 2024). "We also found that two exon junctions in genes BRD9 and NUP210L showed an association with overall breast cancer risk at the Bonferroni-corrected significance of P < 4.3 × 10−6 (0.05/11, 426)." (PMID 38697998, 2024). "Targeting ARID1A phosphorylation pathways, potentially via MAPK inhibitors or BRD4/BRD9 antagonists, could restore its suppressive activity and improve treatment outcomes in breast cancer." (PMID 41572083, 2026). "Additionally, it is noteworthy that in comparison with normal tissues, the S482 locus within the DUF3512 domain of BRD9 displayed a decreased phosphorylation level in breast cancer tissues." (PMID 38303608, 2024). "Analyses by subtypes of breast cancer identified TET2 from APA-WAS in association with ER-negative breast cancer risk at the Bonferroni-corrected significant level and BRD9 from spTWAS in association with ER-negative and TNBC subtypes at the Bonferroni-corrected significant level." (PMID 38697998, 2024). "Several BrD members, namely BRPF1, SMARCA4, BRD7, BRD9, BAZ1B, ATAD2 and BRD4 are significantly upregulated in basal breast cancer subtype (when compared to less aggressive luminal A and normal‐like subtype), which strongly mimics the results obtained for the mRNA‐SI." (PMID 35049055, 2022).
clear cell renal cell carcinoma (5 papers, 2022 to 2025). "I-BRD9 suppressed clear cell renal carcinoma tumor growth, a cancer in which BRD9 is up-regulated by FTO and recruited with SOX17 to enhancers that promote oncogenic gene expression." (PMID 38390898, 2024). "In renal clear cell carcinoma, the combined analysis of BRD9 and other chromatin-regulated genes showed a significant association with the high-risk groups and lower overall survival, providing a prediction model for further research investigating the role of the expression of BRD genes in cancers." (PMID 38255982, 2024).
lung adenocarcinoma (5 papers, 2015 to 2025). A carcinoma that arises from the lung and is characterized by the presence of malignant glandular epithelial cells. "The genes CEP72, BRD9, TRIP13, SLC9A3, SDHA, SLC6A19 and PDCD6 did not have any predictive role in lung adenocarcinoma prognosis." (PMID 26497366, 2015).
cervical cancer (4 papers, 2019 to 2025). A primary or metastatic malignant neoplasm involving the cervix. "Regarding the aberrant methylation status of these genes, it has been described that BRD9 promoter methylation is associated with increased overall and progression-free survival in cervical cancer." (PMID 39858027, 2025). "Based on fluorescence in situ hybridization (FISH), a research indicated that the protein of BRD9 overexpressed in cervical cancer." (PMID 31504061, 2019).
Multiple Myeloma (3 papers, 2022 to 2024). "Ribosome biogenesis stimulation and BRD9 overexpression play critical roles in the development of multiple myeloma malignancy." (PMID 39162964, 2024).
myelodysplastic syndrome (3 papers, 2023 to 2025). A clonal hematopoietic disorder characterized by dysplasia and ineffective hematopoiesis in one or more of the hematopoietic cell lines. "SF3B1 mutations, which are prevalent in myelodysplastic syndrome (MDS) and leukemia, result in missplicing of Brd9 and a subsequent loss of ncBAF at CTCF-associated loci." (PMID 40523422, 2025).
pancreatic cancer (3 papers, 2019 to 2024). "In addition, pharmacological inhibition of BRD9 significantly reduced the tumorigenesis in patient-derived xenografts mouse models and eliminated CSCs in tumors from pancreatic cancer patients." (PMID 37739089, 2024). "Altogether, the results using resected patient tumor samples indicated that BRD9 inhibition by a small molecule compound can efficiently target and eliminate the CSC subpopulation of pancreatic cancer cells, thus confirming our prior discoveries on PDAC cell lines." (PMID 37739089, 2024).
Uterine Leiomyosarcoma (3 papers, 2022 to 2025). "Recently, BRD9 has been shown to be associated with the pathogenesis of uterine leiomyosarcoma, suggesting that BRD9 may have an impact on uterine disorders." (PMID 38255982, 2024). "Recently, the critical role of BRD9 in the pathogenesis of uterine leiomyosarcoma has been identified." (PMID 38255982, 2024). "Notably, BRD9 has been shown to play an important role in the uterine cancer leiomyosarcoma." (PMID 38255982, 2024).
acute leukemia (2 papers, 2022 to 2024). A clonal (malignant) hematopoietic disorder with an acute onset, affecting the bone marrow and the peripheral blood. "RNA-seq analysis of acute leukemia and MM cells revealed both unique and common signaling pathways affected by BRD9 degradation, with common pathways including those associated with regulation of inflammation, cell adhesion, DNA repair and cell cycle progression." (PMID 35853853, 2022). "We used QA-68, as well as BRD9 knockdown (KD) by RNA interference and CRISPR KO, as tools to demonstrate a robust dependency on BRD9 in the context of MM and acute leukemia." (PMID 38610997, 2024). "We also demonstrated the potential for BRD9 targeting to potentiate the antitumor effects of chemotherapy drugs and targeted therapies as a novel treatment strategy for MM and acute leukemia." (PMID 38610997, 2024). "Our findings support further development of therapeutic targeting of BRD9, alone or combined with other agents, as a novel strategy for acute leukemias and MM." (PMID 35853853, 2022). "We also explore the potential for BRD9 targeting to enhance antileukemic effects of chemotherapeutic agents and targeted inhibitors as a novel therapeutic strategy for acute leukemia and MM." (PMID 35853853, 2022). "Taken together, our findings support further development of therapeutic targeting of BRD9, alone or combined with other agents, as a novel strategy for acute leukemias and MM." (PMID 35853853, 2022). "The studies reported herein reveal a BRD9 dependency in acute leukemia and MM and highlight its importance for cell growth and signaling in these diseases." (PMID 35853853, 2022). "Our conclusion is that while BRD9 may play a role in maintenance of MYC expression in some acute leukemia and MM cells, it does not play a universal role in maintenance of MYC expression." (PMID 35853853, 2022).
diffuse large B-cell lymphoma (2 papers, 2022 to 2024). "The following six types of cancer with genetic alteration had especially high copy number amplification of BRD9: ACC, lymphoid neoplasm diffuse large B‐cell lymphoma (DLBC), KIRC, MESO, pancreatic adenocarcinoma (PAAD) and thyroid carcinoma (THCA)." (PMID 38303608, 2024).
glioma (2 papers, 2024). A benign or malignant brain and spinal cord tumor that arises from glial cells (astrocytes, oligodendrocytes, ependymal cells). "Conversely, low expression of BRD9 was linked to a unfavourable outcome for OS in lower grade glioma (LGG) brain cancers." (PMID 38303608, 2024).
lymphoma (2 papers, 2019 to 2025). A malignant (clonal) proliferation of B- lymphocytes or T- lymphocytes which involves the lymph nodes, bone marrow and/or extranodal sites. "In 3 disease types — pancreatic ductal adenocarcinoma, UVM, and lymphoma — the MYC pathway is activated through alternative splicing in PPP2R5A or BRD9." (PMID 40694421, 2025).
Myelodysplasia (2 papers, 2023 to 2024). Clonal hematopoietic stem cell disorders characterized by dysplasia (ineffective production) in one or more hematopoietic cell lineages, leading to anemia and cytopenia. "The primary mice also developed significant myelodysplasia (observation period <12 months); however, the transplanted mice died earlier, suggesting that prolonged stress condition under a transplant setting may enhance the phenotype of Brd9 depletion." (PMID 38102116, 2023).
myeloid leukemia (2 papers, 2020 to 2025). A clonal proliferation of myeloid cells and their precursors in the bone marrow, peripheral blood, and spleen. "Further study found that mutant SF3B1 suppressed levels of full-length BRD9 protein without generating a truncated BRD9 protein in UM (MEL270) or myeloid leukemia (K562) cells that express SF3B1K700E." (PMID 32905346, 2020).
prostate tumor (2 papers, 2021 to 2022). "BRD9 is overexpressed in human prostate tumour tissue, playing a role as a diagnostic biomarker." (PMID 34944438, 2021).
renal carcinoma (2 papers, 2024 to 2025). A carcinoma arising from the epithelium of the renal parenchyma or the renal pelvis. "Similarly, BRD9 also showed elevated expression in tissue samples from LIHC, LUAD, LUSC, COAD, READ, STAD and renal cancer." (PMID 38303608, 2024).
thyroid cancer (2 papers, 2024 to 2025). "They hypothesized that BRD9 promotes tumor growth in thyroid cancer by activating the MAPK/ERK signaling pathway." (PMID 40804316, 2025).
uterine cancer (2 papers, 2022 to 2024). Primary or metastatic malignant neoplasm involving the uterine corpus and/or the cervix. "Accordingly, the present study aimed to determine whether and how BRD9 contributes to aberrant uLMS cell growth, with important implications for the development of novel treatment options for this highly aggressive uterine cancer." (PMID 35883603, 2022). "Therefore, BRD9 constitutes a specific vulnerability in malignant uLMS, and targeting non-BET BRD proteins in uLMS may provide a promising and novel strategy for treating patients with this aggressive uterine cancer." (PMID 35883603, 2022).